SPAG6 (sperm associated antigen 6)
Description:
Important for structural integrity of the central apparatus in the sperm tail and for flagellar motility.
Synonyms: PF16; Repro-SA-1; CT141; FAP194; CFAP194
Tractability: Antibody: its Gene Ontology location is reachable by antibodies, with medium confidence.
Gene: Protein-coding gene on chromosome 10 (22,345,445 to 22,454,224, forward strand). Ensembl gene ENSG00000077327.
Subcellular location: Cytoplasm, cytoskeleton; Cell projection, cilium, flagellum; Cytoplasm, cytoskeleton, cilium axoneme
Subcellular location (Human Protein Atlas): Calyx; End piece; Mid piece; Principal piece
Gene Ontology:
Biological process: cilium movement
Cellular component: axoneme; microtubule cytoskeleton; nucleus; sperm end piece; sperm glycocalyx; sperm midpiece; sperm principal piece; cytoskeleton; motile cilium
Genetic constraint (gnomAD): Loss-of-function variants: 35 observed, 45.78 expected, observed/expected ratio (o/e) 0.76, 90% interval 0.58 to 1.01. The upper end of that interval is the gene's LOEUF score, 1.01, which puts it in group 4 of 6, group 1 being the genes least tolerant of losing a copy. Missense variants: 473 observed, 551.69 expected, observed/expected ratio (o/e) 0.86, 90% interval 0.79 to 0.93. Synonymous variants: 208 observed, 205.45 expected, observed/expected ratio (o/e) 1.01, 90% interval 0.9 to 1.14.
Homologues: Orthologues: macaque SPAG6 (99% identical), pig SPAG6 (97% identical), dog SPAG6 (96% identical), mouse Spag6l (96% identical), rat Spag6l (95% identical), chimpanzee SPAG6 (93% identical), rat Spag6 (92% identical), mouse Spag6 (92% identical), guinea pig Spag6 (91% identical), tropical clawed frog spag6 (87% identical), rabbit SPAG6 (83% identical), zebrafish spag6 (83% identical).
Diseases named in the same sentence as SPAG6 in open-access papers:
SPAG6 is named in the same sentence as 60 diseases in open-access papers, as found by Europe PMC text mining. Sharing a sentence is not in itself a finding about the gene and the disease. The quoted sentences say what the papers report.
Hydrocephalus (13 papers, 2005 to 2025). Hydrocephalus is an active distension of the ventricular system of the brain resulting from inadequate passage of CSF from its point of production within the cerebral ventricles to its point of absorption into the systemic circulation. "Spag6-deficient mice are affected by hydrocephalus and infertility, suggesting that SPAG6 plays an important role in regulating cilial and flagellar motility." (PMID 35232447, 2022). "Although mutations in SPAG6 have not as yet been identified as underlying cases of PCD in humans, Spag6 KO mice have a higher incidence of neonatal death, with ∼50% showing hydrocephalus." (PMID 34028558, 2021). "The majority of Spag6-deficient mice died from hydrocephalus before adulthood, and the surviving males were infertile due to reduced ciliary/flagellar motility." (PMID 26585507, 2015). "Dysfunction of PF16 gives rise to paralyzed flagella in Chlamydomonas It has been reported that Spag6-deficient mice develop hydrocephalus, and the males are sterile due to sperm motility defects." (PMID 25393619, 2014). "Approximately 50% of Spag6-deficient animals died from hydrocephalus before adulthood, and males surviving to maturity were infertile." (PMID 25333478, 2014). "A significant number of Spag6-deficient mice die with hydrocephalus, and surviving males are sterile because of sperm motility defects." (PMID 25333478, 2014). "The presence of the central pair microtubules is absolutely required for motile cilia function within the brain: mice deficient in the central apparatus protein SPAG6 lack the central pair microtubules and develop severe hydrocephalus." (PMID 17683645, 2007). "We concluded that hydrocephalus in the Spag6-deficient mice might be largely due to disrupted polarity in the epithelial cells." (PMID 26585507, 2015). "However, brain ependymal cells of Spag6-deficient mice are functionally defective since hydrocephalus develops." (PMID 25333478, 2014). "Furthermore, several studies have shown that hydrocephalus results from deficiencies in cilia structure components, such as the axonemal proteins Mdnah5 or Spag6." (PMID 17430589, 2007). "The homozygous Spag6 mutant mice were significantly impaired, with 50% of mutant mice exhibiting premature death attributed to the development of hydrocephalus." (PMID 35159146, 2022). "In mice, there is functional redundancy of Spag6 with Spag6-like (Spag6L) and Spag6; Spag6l KO mice have a higher frequency of early embryonic lethality and hydrocephalus." (PMID 34028558, 2021). "The phenotypes reported in the Spag6l KO mice, including hydrocephalus, impaired sperm motility, and abnormal spermatogenesis were not discovered in the Spag6 KO mice." (PMID 35159146, 2022). "Hydrocephalus, which was observed in the Spag6l knockout mice, was not seen in any of the Spag6 KO mice." (PMID 35159146, 2022). "Similarly, the phenotype of Spag6−/− model mice is similar to that of some PCD-associated patients, including hydrocephalus and infertility resulting from a lack of motility related to ependymal cilia and sperm flagella." (PMID 35232447, 2022).
male infertility (7 papers, 2010 to 2026). The inability of the male to effect fertilization of an ovum after a specified period of unprotected intercourse. "A recent study reported that bi-allelic mutations in SPAG6 are related to PCD, accompanied by recurrent respiratory tract infections and male infertility." (PMID 35232447, 2022). "These functional categories contained several genes playing a role in spermatogenesis, fertilization, and determination of the testicular mass, some of which are involved in human and murine male infertility (DDX25 and FKBP6) (SPAG6)." (PMID 20576090, 2010).
myelodysplastic syndrome (6 papers, 2021 to 2025). A clonal hematopoietic disorder characterized by dysplasia and ineffective hematopoiesis in one or more of the hematopoietic cell lines. "Myelodysplastic syndromes (MDS) have a very high risk of transformation into AML, and increased expression of sperm-associated antigen 6 (SPAG6) has been detected in patients with AML transformed by MDS and in patients with new-onset AML." (PMID 38887520, 2024). "In hematological malignancies, researchers have discovered SPAG6 was upregulated in patients with myelodysplastic syndrome (MDS), acute myeloid leukemia (AML), and myeloproliferative neoplasms (MPN)." (PMID 40535772, 2025). "Increased SPAG6 expression is found in a broad range of myeloid cancers and myelodysplastic syndromes." (PMID 34028558, 2021). "Notably, accumulating studies have shown that SPAG6 expression is correlated with the pathogenesis of myelodysplastic syndrome (MDS) and Burkett lymphoma (BL)." (PMID 35227274, 2022). "Many studies’ results have shown that SPAG6 plays a critical role in tumor involvement and progression, especially in myelodysplastic syndrome (MDSC), the common hematological malignancies, and SPAG6 levels were significantly higher than those in solid tumors." (PMID 36199573, 2022).
primary ciliary dyskinesia (6 papers, 2021 to 2025). A rare, genetically heterogeneous, primarily respiratory disorder characterized by chronic upper and lower respiratory tract disease. "In zebrafish, the SPAG6 protein, whose sequence is 80% identical to mouse SPAG6, associates with Ccdc103, a coiled-coil domain-containing protein related to primary ciliary dyskinesia." (PMID 35159146, 2022). "Previous studies have reported that mutations in SPAG6 cause primary ciliary dyskinesia (PCD), but the association between SPAG6 gene variants and the MMAF phenotype has not yet been described." (PMID 35232447, 2022). "The biallelic mutations in SPAG6 are associated with primary ciliary dyskinesia (PCD)." (PMID 40584277, 2025). "SPAG6 is primarily expressed in the lung and testis, and its variants are associated with multi-system dysfunctions involving cilia and flagella, including primary ciliary dyskinesia (PCD)." (PMID 35232447, 2022). "Editor's choice: We show that Ccdc103 regulates myeloid migration and proliferation independent of motile cilia in zebrafish embryos, and that CCDC103 mutations underlying primary ciliary dyskinesia abrogate interactions with the microtubule-stabilizing protein SPAG6." (PMID 34028558, 2021).
breast carcinoma (5 papers, 2017 to 2025). "For example, circMYH9 recruits EIF4A3 to increase the expression of sperm-associated antigen 6 (SPAG6) expression, which promotes breast cancer cell proliferation by activating the PI3K/AKT signaling pathway." (PMID 40710359, 2025). "Sperm-associated antigen 6 (SPAG6) gene, encoding an evolutionarily highly conserved flagellar motility protein, is regulated by promoter hypermethylation in breast cancer." (PMID 41066509, 2025). "For instance, the expression of SPAG6 was increased in breast cancer, osteosarcoma, and ovarian cancer, which could be associated with the pathological grade of the disease." (PMID 39508041, 2024). "Immunohistochemistry on the independent WSG PlanB breast cancer cohort (n = 2241) confirmed comprehensive down-regulation of SPAG6 on the protein level." (PMID 41066509, 2025). "Our in silico analysis of healthy and breast cancer tissues from The Cancer Genome Atlas (TCGA) showed tumour-specific SPAG6 promoter hypermethylation in all molecular subtypes." (PMID 41066509, 2025). "The highest sensitivity for breast cancer detection was however achieved with a combination of SPAG6, PER1 and NKX2-6 (58% sensitivity, cut-off 4.2%, 79% specificity)." (PMID 31741713, 2019). "We propose that SPAG6 may have an important role in triggering the EMT program in luminal breast cancer cells, driving tumour progression and metastasis." (PMID 41066509, 2025). "Therefore, markers were tested in a plasma cohort, achieving a 64% sensitivity for breast cancer detection using SPAG6, PER1 and ITIH5." (PMID 31741713, 2019). "Using these discriminative CpGs on basis of FC, SPAG6 showed a significant higher methylation level in breast cancer (mean of 6.84% in benign controls versus 8.79% in breast cancer, p = 0.0073), DCIS (6.84% versus 8.79%, p = 0.0258) and early invasive breast cancer (6.84% versus 8.80%, p = 0.0168)." (PMID 31741713, 2019). "ROC curve analysis revealed that SPAG6 alone detected breast cancer at 50% sensitivity (cut-off 7.1%, 85% specificity), which could be increased to 60% by adding PER1 (cut-off 5.5%, 85% specificity)." (PMID 31741713, 2019). "In the plasma cohort, on basis of SPAG6, PER1 and ITIH5, sensitivity for breast cancer detection was 64%." (PMID 31741713, 2019). "Although liquid biopsy remains challenging, a combination of SPAG6, NKX2-6, ITIH5 and PER1 (SNiPER) provides a promising tool for blood-based breast cancer detection." (PMID 31741713, 2019). "Accordingly, we identified SPAG6, PER1 and NKX2-6 as novel potential biomarkers for minimally invasive breast cancer detection." (PMID 31741713, 2019). "In the current study, we identified and evaluated SPAG6, PER1 and NKX2-6 as novel epigenetic biomarkers for liquid biopsy-based early breast cancer detection." (PMID 31741713, 2019). "Subsequent ROC curve analysis on basis of validation cohort specific CpGs revealed significant results for a combination of SPAG6 and PER1, achieving breast cancer detection with 25% sensitivity." (PMID 31741713, 2019). "Based on TCGA analysis and the defined criteria, we identified ten potential candidate genes of which SPAG6, PER1 and NKX2-6 proved suitable for early breast cancer detection after an initial validation in breast cancer cell lines and a small cryoconserved tissue cohort." (PMID 31741713, 2019). "Basal-like breast cancers frequently show low methylation levels of tumor suppressor genes, single CpGs of SPAG6, PER1, NKX2-6 and ITIH5 however showed a higher methylation frequency in this molecular breast cancer subtype (59%, 42%, 52% and 41%, respectively)." (PMID 31741713, 2019). "A combination of SPAG6 and NKX2-6 revealed a sensitivity of 27% for breast cancer detection (cut-off methylation 6.9%, 85% specificity), which could be increased to 31% using a combination of SPAG6 and PER1 (cut-off 7.7%, 85% specificity)." (PMID 31741713, 2019).
breast carcinoma (continued). "Moreover, we determined methylation of SPAG6 and L1TD1 in 5 breast cancer, 2 colon cancer, 2 ovarian cancer, 2 pancreatic cancer as well as 2 head and neck cancer cell lines." (PMID 28093071, 2017). "Breast cancer patients showed a non-significant higher methylation frequency for SPAG6 (mean of 6.6% in benign controls versus 8.4% in breast cancer cases, p = 0.2536), PER1 (2.6% versus 4.8%, p = 0.5792), NKX2-6 (1.3% versus 2.9%, p = 0.1898) and ITIH5 (6.8% versus 5.9%, p = 0.9343)." (PMID 31741713, 2019). "However, increases in SPAG6, PER1, NKX2-6 and ITIH5 promoter methylation may not be confined to breast cancer and therefore needs to be tested in non-breast cancer patients such as colorectal- and lung cancer patients, the second and third most common cancers in women." (PMID 31741713, 2019).
non-small cell lung carcinoma (4 papers, 2017 to 2022). A group of at least three distinct histological types of lung cancer, including non-small cell squamous cell carcinoma, adenocarcinoma, and large cell carcinoma. "Interestingly, reduced expression of SPAG6, which is transcriptionally regulated by tumor specific DNA methylation, has been revealed in non-small-cell lung cancer." (PMID 35227274, 2022).
acute myeloid leukemia (3 papers, 2018 to 2025). Acute myeloid leukemia (AML) is a group of neoplasms arising from precursor cells committed to the myeloid cell-line differentiation. "Sperm-associated antigen 6 (SPAG6) is a risk factor for childhood acute myelogenous leukemia." (PMID 29416790, 2018).
asthenozoospermia (3 papers, 2022 to 2023). "our findings expand the understanding of genetic defects in the SPAG6 gene, which is a potential pathogenic factor for syndromic severe asthenozoospermia, such as PCD, and also for non-syndromic asthenoteratozoospermia with the MMAF phenotype." (PMID 35232447, 2022). "The male Spag6 knockout mice were infertile and characterized by abnormal sperm flagella, such as the loss of central microtubules, disorganized ODFs and disrupted fiber sheaths.In a study of 247 patients with asthenospermia, flagellar abnormalities were frequently detected." (PMID 37152951, 2023).
Burkitt lymphoma (3 papers, 2022 to 2025). A rare form of malignant mature B-cell non-Hodgkin lymphoma. "Another study conducted on a mouse model of Burkitt lymphoma confirmed that SPAG6 facilitated the proliferation of Burkitt lymphoma cells by activating the PTEN/PI3K/AKT signaling pathway." (PMID 40535772, 2025). "Zhang confirmed that SPAG6 inhibited apoptosis and promoted cell proliferation through the PTEN/PI3K/AKT pathway in Burkitt’s lymphoma." (PMID 39508041, 2024).
infertile (3 papers, 2007 to 2022). "Its mammalian orthologue, sperm-associated antigen 6 (Spag6), was first cloned by screening a human cDNA library using serum from an infertile man who had a high titer of anti-sperm antibodies in his blood." (PMID 35159146, 2022). "Males that survive to adulthood are infertile with abnormalities in sperm structure and motility, indicating that SPAG6 is also required to maintain the structural integrity of sperm." (PMID 17683645, 2007).
leukemia (3 papers, 2019 to 2021). A malignant (clonal) hematologic disorder, involving hematopoietic stem cells and characterized by the presence of primitive or atypical myeloid or lymphoid cells in the bone marrow and the blood. "Depletion of SPAG6 is associated with reduced proliferation of these leukemia lines, implying that its increased expression contributes to their hyperplasia." (PMID 34028558, 2021).
lung carcinoma (3 papers, 2019 to 2024). "In contrast, SPAG6 demonstrated decreased expression in lung cancer and bladder cancer owing to high methylation of its promoter, and was considered a tumor suppressor gene in these cancers." (PMID 39508041, 2024). "Conversely, SPAG6 expression is reduced in some tumors, such as lung cancer, owing to promoter methylation." (PMID 39508041, 2024).
myeloproliferative neoplasm (3 papers, 2024 to 2025). A clonal hematopoietic stem cell disorder, characterized by proliferation in the bone marrow of one or more of the myeloid (i.e., granulocytic, erythroid, megakaryocytic, and mast cell) lineages. "Nevertheless, the specific function of SPAG6 in BCR::ABL1 negative myeloproliferative neoplasms (MPNs) has been clearly elucidated by Ding and coauthors." (PMID 38827026, 2024).
prostate carcinoma (3 papers, 2013 to 2017). A carcinoma that arises from epithelial cells of the prostate gland. "Spontaneous tumor immune response was also detected for SPAG6 in sera from patients with gastric cancer, melanoma and prostate cancer." (PMID 29190970, 2017).
lung squamous cell carcinoma (2 papers, 2017 to 2025). "However, analyses of gene expression microarray data indicate that low SPAG6 expression is associated with a shorter OS of lung squamous cell carcinoma patients and low L1TD1 expression with a shorter OS of lung adenocarcinoma patients." (PMID 28093071, 2017). "Accumulating evidence indicates SPAG6 regulates oncogenic processes in multiple malignancies, with upregulated expression in lung squamous cell carcinoma correlating with tumor invasion." (PMID 40535772, 2025). "In lung squamous cell carcinoma patients SPAG6 SNVs were seen in only 2%." (PMID 28093071, 2017).